INS (insulin)
Diseases named in the same sentence as INS in open-access papers (continued):
Sharing a sentence is not in itself a finding about the gene and the disease.
diabetes (continued). "Several pharmacological interventions have been used to control hyperglycaemia, including insulin therapy for type 1 diabetes mellitus (T1DM) and non-insulin medications for type 2 diabetes mellitus (T2DM)." (PMID 41186211, 2025). "In this context, physical activity is an effective strategy in both prevention and management of diabetes by improving key metabolic markers such as HbA1c, insulin resistance, and fasting insulin." (PMID 41300761, 2025). "This study highlights the potential long-term benefits of CGM in insulin-treated older adults with diabetes and ADRD and the need for clinical trials in this population." (PMID 41329488, 2025). "Type 2 diabetes mellitus is a disorder affecting glucose and insulin mechanisms, which can lead to severe impacts on micro- and macrovascularization, potentially contributing to the development of diabetic complications." (PMID 40427019, 2025). "Another study of B cells in the NOD mice diabetes model was aimed to clarify the relations between B-cell receptor affinity towards insulin and the phenotypes of B cells during T1DM progression." (PMID 40979707, 2025). "Type 2 diabetes mellitus (T2DM) is a global health challenge characterized by insulin resistance and pancreatic β-cell dysfunction." (PMID 41373625, 2025). "It has been observed that whole grain consumption has significant effects on medium‐ and long‐term parameters including reduction of fasting blood glucose and plasma insulin concentrations in diabetics." (PMID 40688606, 2025). "For individuals with diabetes requiring both prandial and basal insulin throughout the day, managing multiple injections can be burdensome and increase the risk of dosing errors." (PMID 41531706, 2025). "Oral insulin nanotherapeutics provide an effective strategy for diabetes management and improved patient compliance." (PMID 41463606, 2025). "In the animal model of diabetes induced by alloxan bilberry extract (2 g/kg)-reduced blood glucose, elevated insulin levels and normalized serum lipid profile were observed." (PMID 40724509, 2025). "Example measures for Empowering People with diabetes who use insulin (PWDI) to self‐manage and arrange self‐management of diabetes in hospital." (PMID 40696540, 2025). "Diabetes constitutes a chronic metabolic disorder typified by insulin resistance or inadequate insulin secretion." (PMID 39932979, 2025). "If the body cannot counteract insulin resistance by producing more insulin, this can result in hyperglycemia and eventually type 2 diabetes mellitus." (PMID 40040878, 2025). "Regarding medication, 42.0% of participants were on oral medication, 25.5% on insulin injections, 18.0% used both, and 14.5% managed their diabetes with diet regimens alone." (PMID 40922237, 2025). "Diabetes mellitus is a metabolic disorder characterized by hyperglycemia, which arises from defects in insulin secretion, impaired insulin function or both." (PMID 41185072, 2025). "Insulin therapy among patients with diabetes also varied significantly across BMI categories: 11.0% in underweight, 9.4% in healthy-weight, 12.3% in overweight and 20.4% in obesity (p<0.001)." (PMID 40967652, 2025). "The significant role of nesfatin-1 in glucose and insulin metabolism has been emphasized in various studies; however, the results concerning its connection to diabetes and insulin resistance show considerable variability." (PMID 40559404, 2025). "Insulin resistance is one of the primary characteristics of diabetes, and OS suppresses insulin signaling through multiple pathways." (PMID 40599237, 2025). "Diabetes is characterized by chronic hyperglycemia due to insufficient insulin production or impaired insulin function." (PMID 40238356, 2025). "Implementing the CDCES insulin dosing policy led to increased communication with families in between regularly scheduled clinic visits and a higher proportion of youth with diabetes achieving target glycemic goals with limited hypoglycemia." (PMID 41283065, 2025).
diabetes (continued). "Glycemic markers and insulin resistance indices were markedly worse in diabetics, who displayed significantly higher fasting glucose, insulin, HOMA-R, and HbA1c levels (all P < 0.001)." (PMID 41030851, 2025). "Many studies have focused on insulin, its signaling, and resistance in both peripheral and central tissues as the primary pathological mechanism linking AD and diabetes." (PMID 40381169, 2025). "Type 2 diabetes mellitus (T2DM) is a chronic metabolic disorder in which the pancreas is unable to produce adequate insulin or the body resists insulin." (PMID 40672460, 2025). "Diabetes mellitus, a metabolic disorder characterized by elevated blood glucose levels, arises from defects in insulin secretion, insulin action, or both." (PMID 39835172, 2025). "Elevated levels of TMAO have been shown to impair glucose-stimulated insulin secretion, reduce β-cell mass, and worsen glucose tolerance, all of which can contribute to the progression of diabetes." (PMID 40177494, 2025). "As it was mentioned by Imenshahidi, M., Gannon MC, and González-Ortiz M., glycine supplementation has been shown to enhance several aspects of metabolic syndrome, such as diabetes, obesity, hyperlipidemia, and hypertension by increasing insulin secretion." (PMID 40149650, 2025). "Such mice with K-cell-specific insulin production are protected from development of streptozotocin (STZ)-induced diabetes and show preserved glucose tolerance upon such chemical destruction of the β-cells." (PMID 40024571, 2025). "Exercise and daily physical activity are important non-pharmacological strategies to improve blood glucose regulation, insulin sensitivity and metabolic control in individuals with type 1 diabetes mellitus." (PMID 40806227, 2025). "Traditionally regarded as an anti-insulin hormone, glucagon was soon employed in clinical practice to treat insulin-induced hypoglycemic coma in individuals with type 1 diabetes mellitus (T1DM)." (PMID 41149695, 2025). "Insulin autoantibody titers correlate with disease progression in humans, but insulin autoantibodies are often transient and wane by diabetes onset." (PMID 41259806, 2025). "Central to the pathogenesis of diabetes is the dysfunction of pancreatic β-cells, which are crucial for regulating blood glucose levels through insulin secretion." (PMID 40154614, 2025). "For example, virtual reality simulations are being piloted in diabetes care to let patients visualize how glucose levels respond to food intake, activity, or insulin administration." (PMID 41282582, 2025). "Sex differences in diabetes outcomes have been reported in previous research, potentially due to biological factors (such as hormonal differences affecting insulin sensitivity) or differences in health behaviors." (PMID 40503240, 2025). "Type 2 diabetes mellitus, which accounts for approximately 90% of all patients with diabetes mellitus, develops mainly due to insufficient sensitivity to insulin." (PMID 41180182, 2025). "We believe that because of the rising global prevalence of diabetes mellitus, a commentary on emerging insulin analogues as treatment options is important for the medical community." (PMID 41155876, 2025). "Type 2 diabetes mellitus (T2DM), which accounts for 90–95% of all diabetes cases, is a chronic metabolic disorder characterized by insulin resistance and impaired insulin secretion." (PMID 40565232, 2025). "The human body has a limited ability to regenerate insulin-producing cells, which are crucial for managing diabetes." (PMID 39741186, 2025). "Adherence to the recommendations provided by the Society for Pediatric and Adolescent Diabetes for children and adolescents with type 1 diabetes is essential in managing these risks and adjusting insulin levels as appropriate." (PMID 38954647, 2025). "Physical exercise remains a cornerstone of diabetes management due to its positive effects on glucose regulation, insulin sensitivity, and cardiovascular health." (PMID 40792127, 2025).
diabetes (continued). "Background/Objectives: Postprandial glucose variability is a key challenge in diabetes management for patients receiving multiple daily insulin injections (MDI)." (PMID 41470777, 2025). "Diabetes and smoking mediated the use of exogenous insulin (ukb-b-7350) in osteoarthritis (ieu-a-1169) Mendelian randomization mediating role in the analysis of evaluation." (PMID 41398760, 2025). "Subsequent intensification of diabetes management (e.g., insulin initiation, inpatient stabilization) can further weaken the association between baseline HbA1c and clinical outcomes." (PMID 41374452, 2025). "The first of these was recognising and incorporating the expertise of PWDI in identifying diabetes management needs and ongoing insulin adjustments." (PMID 40324886, 2025). "Clinical benefits include improved glucose control, insulin production, and considerable pain reduction in diabetes complications." (PMID 40141412, 2025). "Artificial intelligence (AI)-driven insulin pumps and closed-loop devices, also known as artificial pancreas, have become groundbreaking tools for improving diabetes care." (PMID 41294766, 2025). "At present, the management of diabetes primarily focuses on enhancing glucose uptake through improved insulin delivery." (PMID 41009376, 2025). "In the pathogenesis of prediabetes and diabetes, inflammatory response, nutrition, intestinal permeability, glycolipid metabolism, insulin sensitivity, and energy homeostasis play an important role, as reported by Gurung M’s review." (PMID 39997751, 2025). "A randomized controlled, multicentric trial was conducted in 204 people with diabetes (60% type 2 diabetes) treated with insulin to assess the efficacy of ESYSTA." (PMID 40661654, 2025). "Anti-inflammatory agents including salsalate and IL-1 blockers, moderate the progression of diabetes by increasing insulin levels and β-cell function." (PMID 40491590, 2025). "Meta-analyses have confirmed these patterns, showing RYGB achieving higher rates of diabetes remission, reduced need for medication, and improved insulin sensitivity compared with SG." (PMID 41246693, 2025). "Insulin Sensitization: Glycyrrhiza glabra modulates insulin signaling pathways, enhances glucose uptake, and reduces insulin resistance, thereby mitigating diabetes-induced hepatic dysfunction." (PMID 40136563, 2025). "Second, the study was conducted in a “free-living” environment, enhancing its external validity and relevance to real-world settings, as participants adhered to dietary interventions while managing their diabetes with automated insulin delivery systems." (PMID 40045281, 2025). "Diabetes mellitus is a chronic metabolic disorder characterized by persistent hyperglycemia resulting from insulin resistance, reduced insulin secretion, or both." (PMID 41567897, 2025). "SHAP results showed that the top 5 variables included TyG, HDL, Insulin therapy, Diabetes course, and HbA1c." (PMID 41293734, 2025). "Diabetes mellitus is a chronic metabolic disorder characterized by persistent hyperglycemia due to insufficient insulin production or the body’s ineffective use of insulin." (PMID 39319898, 2025). "For instance, in the SIRD cluster, individuals with a low NRE tended to have much lower insulin resistance than what is typical for this severe subtype of diabetes." (PMID 40715719, 2025). "These adolescents also showed greater reluctance to adopt insulin delivery technologies, reinforcing the role of language and cultural context in shaping engagement with diabetes management tools." (PMID 40723075, 2025). "Patients who develop diabetes after infection resemble those with type 2 diabetes mellitus, and have been reported to have both impaired insulin secretion and increased insulin resistance, which are two major causes of type 2 diabetes mellitus." (PMID 39861420, 2025). "In experimental models of diabetes, a reduced level of bone–implant contact has been shown, which was reversed by means of treatment with insulin." (PMID 40077012, 2025).
diabetes (continued). "Insulin pump therapy significantly improves glycemic control, reduces hypoglycemia frequency, and enhances the quality of life for individuals with type 1 diabetes mellitus." (PMID 41146752, 2025). "Implantable insulin pumps and closed-loop delivery systems (artificial pancreas) revolutionized human diabetes management." (PMID 41012437, 2025). "The Diabetes Control and Complications Trial demonstrated that intensive insulin therapy for tighter glycemic control mitigated some of the vascular complications of diabetes, but this benefit was offset by an increased risk of hypoglycemic episodes." (PMID 40759576, 2025). "Closed-loop control systems, also known as artificial pancreases, can automate insulin therapy for diabetes treatment." (PMID 40574088, 2025). "But in the context of insulin therapy it is worth noting that <5% of people with diabetes have type 1 diabetes (T1DM), despite their generally earlier onset of the condition (≈50% <18 years) and their generally long life expectancy." (PMID 40035222, 2025). "In this retrospective cohort study of over 1000 patients, endocrine-metabolic dysfunctions, particularly non-insulin-treated diabetes and hypothyroidism and male sex were independently associated with increased odds of DCM in this cohort." (PMID 41153651, 2025). "Upon discharge, she continued metformin 1000 mg + dapagliflozin 5 mg twice daily, started insulin glargine 8 UI per day and was referred to a diabetes clinic." (PMID 40539164, 2025). "By stabilizing GLP-1R in its active conformation, exenatide enhances glucose-stimulated insulin secretion, suppresses glucagon release, and slows gastric emptying—actions critical for managing type 2 diabetes mellitus." (PMID 41226200, 2025). "P5, who had never before managed hyperglycaemia, was called on a Saturday to see an elderly patient with diabetes complicated by urosepsis whose diabetes had been treated reactively with one-off insulin doses but remained hyperglycaemic." (PMID 40973362, 2025). "Research in this area has the potential to identify interventions that can protect insulin secretion and insulin response organs from metabolic and inflammatory stress and to improve glycemic control in individuals with metabolic syndrome and diabetes." (PMID 41373704, 2025). "The link between sleep and diabetes is believed to be related to pathophysiological mechanisms such as energy homeostasis, insulin sensitivity, beta-cell function and autonomic neuropathy." (PMID 41425203, 2025). "Sixty-three percent of the study participants make skinfolds during their insulin injection, and those trained by the diabetes educators are performing well in this regard." (PMID 40376558, 2025). "Adverse skin reactions to continuous glucose monitors (CGMs) and devices for continuous subcutaneous insulin infusions (CSIIs) (“diabetes medical devices” (MDs)) are well known." (PMID 40331898, 2025). "Insulin, the prototypical pharmaceutical agent for the treatment of diabetes, was initially derived and purified from the pancreatic tissue of a canine in 1921 and subsequently validated in a 12-year-old adolescent in 1922." (PMID 40038239, 2025). "The inhibition of GSK3A improves insulin response, suggesting possible beneficial effects on insulin resistance, metabolic syndrome, and diabetes." (PMID 40807372, 2025). "A similar case happened with Medtronic’s Mini-med insulin pumps, which were designed to deliver controlled dosages of insulin to manage diabetes." (PMID 41383269, 2025). "Diabetes mellitus (DM) refers to a group of chronic metabolic disorders marked by hyperglycemia resulting from dysfunctions in insulin action, synthesis, or both." (PMID 40546344, 2025). "Overall, metformin and insulin are important for diabetes management in elderly people, but diabetes also strongly affects the health of their teeth and gums." (PMID 40896019, 2025).
diabetes (continued). "LSG/DJB significantly increased the 3-, 6-, and 12-month TIR to 96%, 93%, and 89%, respectively, and decreased the time-above range to 4%, 7%, and 11%, respectively, indicating high-dose insulin withdrawal and complete diabetes remission." (PMID 41938286, 2025). "Diabetes is a complex metabolic condition characterized by cerebral insulin resistance and impaired insulin signaling, which result in reduced neuronal glucose utilization and promote oxidative stress and neuroinflammation." (PMID 41356840, 2025). "IR, defined by a diminished responsiveness of insulin-sensitive tissues to physiological insulin levels, is a key contributor to numerous conditions, such as ischemic stroke, type 2 diabetes mellitus, atherosclerosis, and metabolic syndrome." (PMID 40895101, 2025). "This analysis demonstrates that out-of-pocket costs for non-insulin diabetes medications can be extremely high for patients with employer-sponsored insurance, with those taking multiple drug classes facing potential annual costs approaching $3,000." (PMID 40358737, 2025). "Insulin-resistant β-cells in diabetes cause WSP to be downregulated, which reduces insulin production and causes pancreatic islet cell failure." (PMID 40381169, 2025). "Diabetes mellitus refers to a group of metabolic disorders characterized by chronic hyperglycemia due to defects in insulin secretion and/or function." (PMID 41459495, 2025). "During follow-up, 11 patients required initiation or intensification of anti-diabetic treatment (only one patient with a pre-existent diabetes required insulin), but glycemic profile remained worse compared to baseline." (PMID 41323967, 2025). "Contrary to the prevalent understanding of insulin resistance as the primary factor, 95% of the patients in our study demonstrated high insulin sensitivity while still having diabetes." (PMID 40860623, 2025). "This would decrease insulin secretion and increase glucagon secretion, a situation similar to that seen in diabetes and starvation." (PMID 40305364, 2025). "Diabetes mellitus is a chronic metabolic disease, characterized by persistent hyperglycemia resulting from defects in insulin secretion or action, and has emerged as a major global health threat." (PMID 40565658, 2025). "Nonetheless, given that the average age and BMI in this group was low and that they all need insulin treatment, we expect that the presence of other diabetes types is limited." (PMID 39898772, 2025). "investigate the association between chrononutrition factors (meal regularity, meal timing and meal frequency) and glycemic outcomes in terms of glucose indices, insulin indices and incidence of diabetes among adults." (PMID 39951411, 2025). "Diabetes mellitus is a metabolic disorder characterized by persistent hyperglycemia resulting from impaired insulin secretion, insulin function, or a combination of both." (PMID 40356973, 2025). "Early treatment intensification with DPP4i within two years of diabetes diagnosis reduces glycemic variability, improves glycemic durability, and delays insulin initiation." (PMID 40342458, 2025). "The limitation of this study is that determining the impact of different treatment strategies (diet, blood glucose-lowering drugs, and insulin) on DSC among diabetes patients was beyond the scope of this study." (PMID 40084339, 2025). "Both WT and nephrin-Y3F mice had comparable diabetes induction, with similar HbA1c% and total units of insulin being required for treatment." (PMID 40510123, 2025). "Specifically, Tyr improves insulin sensitivity by increasing glucose uptake and fatty acid metabolism, thereby alleviating symptoms of diabetes." (PMID 40298838, 2025). "This phenomenon leads to impaired insulin secretion and β-cell apoptosis, thereby exacerbating hyperglycemia and contributing to the progression of diabetes." (PMID 40002577, 2025).